SIRT2 (sirtuin 2)
Diseases named in the same sentence as SIRT2 in open-access papers (continued):
Sharing a sentence is not in itself a finding about the gene and the disease.
glioblastoma (12 papers, 2014 to 2025). The most malignant astrocytic tumor (WHO grade IV). "There, SIRT2 activation mediates the antiproliferative function of resveratrol specifically on glioblastoma stem cells, thus underlining the importance of cellular context in determining specific roles for sirtuins." (PMID 28994177, 2017). "SIRT2 plays a significant role in glioblastoma by promoting the proliferation and tumorigenicity of glioblastoma cells, including glioblastoma stem cells." (PMID 40710366, 2025). "For example, in glioblastoma, SIRT2 deacetylates p73, a tumor suppressor, thereby inactivating its transcriptional activity and fostering tumor growth." (PMID 40710366, 2025). "The results showed that the mean SIRT2-LI was significantly higher in glioblastoma samples compared with diffuse astrocytoma samples and normal controls." (PMID 40710366, 2025). "Using immunohistochemistry to analyze samples from 23 glioblastoma patients, 8 diffuse astrocytoma patients, and 5 healthy individuals, it established a SIRT2 labeling index (SIRT2-LI) to measure the percentage of cells with SIRT2 localized in the nucleus." (PMID 40710366, 2025). "In particular, Funato and colleagues showed that the SIRT-2-mediated inactivation of tumor suppressor p73 is crucial in the proliferation and tumorigenicity of glioblastoma cells, thus making SIRT-2 inhibition by AGK2 or AK7 a valid anti-cancer treatment." (PMID 36080416, 2022). "The acetylation of p73 by SIRT2 confirmed the requirement for SIRT2 for the growth and survival of human glioblastoma cells, as well as for the formation and progression of glioblastomas in mouse models." (PMID 33921128, 2021). "SIRT2 activity mediated the inhibitory action of RES on the cell cycle of glioblastoma stem cells derived from human patients." (PMID 31159437, 2019). "In the same study, the SIRT2‐selective inhibitor AGK2 displayed antiproliferative activity against glioblastoma multiforme tumorspheres." (PMID 28994177, 2017). "On the other hand, SIRT2 activity has been reported to exert an opposite effect in the context of glioblastoma." (PMID 28994177, 2017). "By inhibiting SIRT2, it may be possible to restore the function of p73, potentially reducing the tumorigenicity of glioblastoma cells." (PMID 40710366, 2025). "The p73 activity was also inhibited through acetylation by SIRT2 in glioblastoma cells." (PMID 33921128, 2021). "Furthermore, SIRT2 mRNA expression was reduced in anaplastic oligodendroglioma, glioblastoma, clear cell renal carcinoma, and prostate carcinoma." (PMID 31932479, 2020). "Thus, the SIRT2-mediated inactivation of p73 is a crucial mechanism in the tumorigenicity of glioblastoma, suggesting that targeting SIRT2 could be a promising therapeutic strategy." (PMID 40710366, 2025). "SIRT2, a NAD-dependent histone deacetylase, is required for glioblastoma stem cells proliferation and tumorigenicity." (PMID 34749806, 2021). "Nevertheless, consistent with the SIRT2 knockdown results, AGK2 treatment inhibited the colony formation and induced apoptosis in GB2, GB4, GB11, and GB16 primary glioblastoma cells." (PMID 34650436, 2021). "At the transcriptional level, treatment with the nitrocompounds resulted in the downregulation of G6PD, SIRT2, and VEGF gene expression, which may contribute to reduced glioblastoma cell proliferation and impaired adaptation to hypoxic stress." (PMID 41009654, 2025). "Moreover, RES blocked the proliferation of glioblastoma stem cells without influencing the behavior of neural stem cells in a SIRT2-independent mechanism." (PMID 31159437, 2019).
prostate carcinoma (12 papers, 2017 to 2025). A carcinoma that arises from epithelial cells of the prostate gland. "In prostate cancer, exosomal miR-1275 secreted by cancer cells modulates osteoblast proliferation and activity through targeting the SIRT2/RUNX2 cascade." (PMID 40476182, 2025). "Among the many factors involved in the progression of prostate cancer, SIRT2 plays a unique role by regulating histone acetylation and modulating key signaling pathways." (PMID 39796040, 2024). "Conversely, SIRT2 regulates the cell cycle and suppresses tumorigenesis in gliomas, while promoting proliferation and disease aggressiveness in prostate cancer." (PMID 39796040, 2024). "In this regard, future studies are required to determine the oncogenic or tumor-suppressing effect of SIRT2 in prostate cancer." (PMID 36291902, 2022). "In this section, we discuss the mechanistic roles of nuclear (SIRT1, 6, and 7), cytoplasmic (SIRT2), and mitochondrial sirtuins (SIRT3, 4, and 5) in breast and prostate cancer." (PMID 36291902, 2022). "Analysis of genomic and clinical data in The Cancer Genome Atlas (TCGA) and Gene Expression Omnibus (GEO) has revealed that the HAT P300 and its target H3K18Ac increase during prostate cancer progression, while the HDAC SIRT2 decreases." (PMID 31121824, 2019). "In this study using roughly 1100 patients across multiple databases, we find that the HAT P300 and its target H3K18Ac increase during prostate cancer development and progression, while the HDAC SIRT2 decreases." (PMID 29262808, 2017). "Unfortunately, to date, there are no studies that have investigated the mechanistic role of SIRT2 in prostate cancer." (PMID 36291902, 2022). "The expression of histone H3K18Ac acetylation, and proteins that regulate its acetylation (P300) and deacetylation (SIRT2), has been evaluated in benign prostatic hyperplasia (BPH), high grade prostatic intraepithelial neoplasia (HGPIN), prostate cancer (PCa), and metastases." (PMID 31121824, 2019).
type 2 diabetes (12 papers, 2017 to 2025). "Past researches revealed that SIRT2 could treat type 2 diabetes by regulating mitochondrial quality control." (PMID 35493297, 2022). "Recently, many studies revealed that the dysregulation of SIRT2 activity is a key factor contributing to the pathogenesis of cancer, neurodegenerative diseases, type II diabetes, and bacterial infections, which makes SIRT2 a promising target for pharmaceutical intervention." (PMID 31357491, 2019). "The relationship between type 2 diabetes mellitus (T2DM)‐induced cardiomyopathy and SIRT2 will be studied in the future." (PMID 34028177, 2021). "Human sirtuin 2 (SIRT2), a member of the sirtuin family, has been considered as a promising drug target in cancer, neurodegenerative diseases, type II diabetes, and bacterial infections." (PMID 31357491, 2019). "Subgroup analyses revealed that SIRT2 levels were found to be significantly higher in both microalbuminuric and macroalbuminuric patients compared to patients with type 2 diabetes without nephropathy, with higher levels observed in the macroalbuminuric group." (PMID 41303131, 2025). "The present study demonstrated that serum SIRT2 levels were highest in patients with diabetic nephropathy, significantly exceeding those observed in both healthy controls and patients with type 2 diabetes without nephropathy." (PMID 41303131, 2025). "We demonstrate that Sirt2-dependent GKRP deacetylation improves impaired HGU and suggest that it may be a therapeutic target for type 2 diabetes." (PMID 29296001, 2018). "SIRT2 has been found to regulate metabolism by deacetylating and stabilizing phosphoenolpyruvate carboxykinase (PEPCK1), which is the rate limiting enzyme for gluconeogenesis, linking SIRT2 with type II diabetes." (PMID 28197299, 2017).
viral infection (12 papers, 2019 to 2025). "Outside the context of viral infection, SIRT2 has been implicated in cancer progression." (PMID 37916830, 2023). "The ion channel Piezo1, as a signal node, senses the magnesium concentration and integrates the downstream SIRT2–HIF1α signalling pathway to direct NET formation during the response to viral infection." (PMID 39890818, 2025). "Altogether, our findings have significant ramifications for understanding the function of SIRT2 during viral infection and reflect a necessity for deconvoluting the various enzymatic activities of SIRTs and their functions in human health and disease." (PMID 37916830, 2023). "It is likely that, similar to its function during viral infection, SIRT2 functions in both capacities, depending on the enzymatic activity and substrate." (PMID 37916830, 2023). "The spotlight on sirtuin 2 (Sirt2) in viral infection has intensified in recent years." (PMID 38239506, 2023). "SIRT1 inhibition has also been proposed in the treatment of virus infections, whereas SIRT2 inhibitors might be useful for the treatment of cancer and neurodegenerative diseases." (PMID 33669990, 2021). "Consistent with the results in AML12 cells, K102R or K211R mutant protein level was significantly higher than that of wild-type C/EBPβ in SIRT2-KO murine livers, whereas the viral infection and transcription level were similarly indicated by BLI and qRT-PCR (data not shown)." (PMID 34642310, 2021). "However, very few studies talk about SIRT2 dependent disease progression in bacterial and viral infections." (PMID 32697192, 2020). "Piezo1−/− or Piezo1 upregulation by Yoda1 treatment altered SIRT2 and HIF1α expression in neutrophils, indicating that SIRT2 and HIF1α are likely involved in Piezo1-mediated NET formation in neutrophils during the response to virus infection." (PMID 39890818, 2025). "Based on these findings, we selected five genes—Nampt, Nmnat2, Sirt1, Sirt2, and CD38—that were consistently upregulated in both RD and A549 cells, to evaluate their protein expression levels after viral infection." (PMID 40006932, 2025). "Altogether, our findings expand the understanding of mechanisms underlying HCMV-induced cell cycle dysregulation and point toward regulatory feedback between SIRT2 and CDK2 that can have implications in other viral infections and human diseases." (PMID 37916830, 2023). "Interestingly, previous studies have reported that the NAD+ synthesis or consumption genes NAMPT, SIRT1, SIRT2, and CD38 were upregulated during various viral infections, while Nmnat2 was found to decrease following Zika virus infection." (PMID 40006932, 2025). "Under normal and viral infection conditions, magnesium at a physiological concentration (0.6 mM) increased NET formation and the expression of PAD4, SIRT2 and HIF1α; upregulation of Piezo1 expression by Yoda1 treatment promoted these effects, but Piezo1−/− abolished these alterations." (PMID 39890818, 2025). "Specifically, SIRT1, SIRT2 and SIRT5 have been shown to exhibit potent pro-viral activity by facilitating the replication of a range of viral pathogens, while in certain viral infections, SIRT1, SIRT5, and SIRT6 display anti-viral properties." (PMID 40006932, 2025). "Our data showed that SIRT2–HIF1α, a redox-related mechanism, is required for regulating PAD4–ROS signalling-mediated NET formation in Piezo1−/− neutrophils during the immune response to viral infections." (PMID 39890818, 2025). "Therefore, the results indicated that inhibition of SIRT1 and SIRT2 is not sufficient to block viral infection but suggested that, instead, inhibition of multiple SIRTs is required to inhibit arboviral infection." (PMID 31289184, 2019). "Our findings suggest that inhibition of at least SIRT1 and SIRT2 is required for antiviral activity, since inhibition of either SIRT and of the combination of the specific SIRT1/2 inhibitors did not block viral infection." (PMID 31289184, 2019).
acute myeloid leukemia (11 papers, 2013 to 2024). Acute myeloid leukemia (AML) is a group of neoplasms arising from precursor cells committed to the myeloid cell-line differentiation. "In this regard, high levels of SIRT2 expression are associated with unfavorable prognosis of acute myeloid leukemia." (PMID 36297603, 2022). "For example, Sirt2 has been implicated in the control of IL4i1 expression in blood cells from acute myeloid leukemia (AML)." (PMID 38605962, 2024). "In this study, the associations between SIRT2 expression and molecular and clinical characteristics of patients with acute myeloid leukemia (AML) were evaluated by data from The Cancer Genome Atlas." (PMID 27291931, 2016). "For example, SIRT2 expression is increased in acute myeloid leukaemia mother cells, and downregulating SIRT2 expression promotes apoptosis in HeLa cells." (PMID 35493297, 2022). "We previously reported that SIRT2 inhibition resulted in apoptosis and diminished proliferation of acute myeloid leukemia cells through deacetylation/activation of Akt and subsequent activation of ß-catenin." (PMID 33546767, 2021). "It is of note that SIRT2 is expressed at higher levels in the relapsed patients with acute myelogenous leukemia than the newly diagnosed patients and, consistently, in HL60 downregulating Pgp." (PMID 34067290, 2021). "SIRT2 expression increases in acute myeloid leukemia blasts." (PMID 30081901, 2018). "SIRT2 is the primary cytoplasmic surtuin but shuttles continuously between cytoplasmic and nuclear comparts during interphase, and it is found to be involved in the proliferation and survival of acute myeloid leukemia." (PMID 27291931, 2016). "Similar to our findings in Schwannoma and control Schwann cells, upregulation of SIRT2 mRNA and protein levels has been reported in some cancer cells such as primary acute myeloid leukemia blasts compared to control hematopoietic progenitor cells from healthy individuals." (PMID 24259290, 2013). "In addition, the SIRT2 inhibitor AC93253 has an anti-proliferative effect on AML (acute myeloid leukemia) cells, but the capacity of this compound to induce cellular differentiation remains elusive." (PMID 23460888, 2013). "SIRT2 mRNA levels are significantly elevated in acute myeloid leukemia (AML) blasts compared with those in bone marrow from healthy individuals." (PMID 30081901, 2018). "In acute myeloid leukemia (AML) cell models, SIRT2 promoted the Warburg effect by deacetylating and activating glucose-6-phosphate dehydrogenase (G6PD) enzyme, increasing the production of NADPH, and supporting the biosynthesis of macromolecules that are essential for rapid cell proliferation." (PMID 32117717, 2020).
ovarian carcinoma (11 papers, 2020 to 2025). A malignant neoplasm originating from the surface ovarian epithelium. "Intriguingly, we found that low SIRT2 expression was associated with shorter PFS in ovarian cancer patients receiving platinum-included chemotherapy." (PMID 33207824, 2020). "Therefore, we would like to go deeper into the underlying mechanism of how SIRT2 regulates chemosensitivity in ovarian cancer later on." (PMID 33207824, 2020). "Pharmacological inhibition of SIRT2 using AGK2 also demonstrated anti-metastatic effects, supporting the Fn14–SIRT2–Slug axis as a novel regulatory pathway in ovarian cancer." (PMID 41471349, 2025). "In W1 ovarian cancer cells, our lead structurefor dual Sirt2/HDAC6 inhibition evoked enhanced effects on cell viabilitycompared to single or combination treatment with the unconjugatedSirt2 and HDAC6 inhibitors." (PMID 37902787, 2023). "In ovarian cancer cells, 33 evokedenhanced effects on cell viability compared to single or combinationtreatment with the unconjugated Sirt2 and HDAC6 inhibitors." (PMID 37902787, 2023). "CP administration significantly increases ROS levels to induce SIRT2 expression, resulting in ovarian cancer suppression." (PMID 33921908, 2021). "In this study, we investigated the differential regulation of SIRT2 expression in response to cisplatin treatment in A2780/S and A2780/CP ovarian cancer cell lines." (PMID 33207824, 2020). "To explore the potential role of SIRT2 in ovarian cancer cells, we first analyzed the SIRT2 expression using public databases." (PMID 33207824, 2020). "They found that SIRT2 was significantly downregulated in ovarian cancer tissues and cell lines as compared with normal epithelium counterparts." (PMID 33207824, 2020). "Our study, for the first time, identified the critical role of SIRT2 in the cisplatin response in ovarian cancer." (PMID 33207824, 2020). "Moreover, analysis of the TCGA ovarian cancer cohort further validated the correlations between Fn14, SIRT2, and Slug mRNA expression levels." (PMID 40344622, 2025). "A recent study identified SIRT2 as a key pro-metastatic factor in epithelial ovarian cancer." (PMID 41471349, 2025). "Reduced SIRT2 expression promotes serious ovarian carcinoma migration and invasion, suggesting that SIRT2 may serve as a tumor suppressor and a therapeutic target in ovarian cancer." (PMID 36185333, 2022). "In ovarian cancer cells, enhancing SIRT2 expression paves the way for CP sensitivity." (PMID 33921908, 2021). "SIRT2 showed a lower expression level in tumor tissues than normal tissues in ovarian cancer." (PMID 33207824, 2020). "Additionally, higher SIRT2 expression was correlated with longer progression-free survival (PFS) in ovarian cancer patients with platinum-included chemotherapy." (PMID 33207824, 2020). "Our study proposes that targeting SIRT2 may provide new strategies to potentiate platinum-based chemotherapy in ovarian cancer patients." (PMID 33207824, 2020). "Notably, SIRT2 was markedly downregulated in ovarian cancer tissues as compared with normal tissues." (PMID 33207824, 2020). "This suggested that SIRT2 could be a critical biomarker for indicating the response to cisplatin in ovarian cancer." (PMID 33207824, 2020). "Thus, the specific mechanisms of SIRT2 in ovarian cancer still need further exploration." (PMID 35252174, 2022). "However, the role of SIRT2 in response to cisplatin in ovarian cancer cells remains largely unknown." (PMID 33207824, 2020). "To further explore the role of SIRT2 in cisplatin sensitivity of ovarian cancer cells, next, we transfected FLAG-SIRT2 into A2780/CP cells to transiently overexpress SIRT2." (PMID 33207824, 2020).